VPS11 (VPS11 core subunit of CORVET and HOPS complexes)
Description:
Plays a role in vesicle-mediated protein trafficking to lysosomal compartments including the endocytic membrane transport and autophagic pathways. Believed to act as a core component of the putative HOPS and CORVET endosomal tethering complexes which are proposed to be involved in the Rab5-to-Rab7 endosome conversion probably implicating MON1A/B, and via binding SNAREs and SNARE complexes to mediate tethering and docking events during SNARE-mediated membrane fusion. The HOPS complex is proposed to be recruited to Rab7 on the late endosomal membrane and to regulate late endocytic, phagocytic and autophagic traffic towards lysosomes. The CORVET complex is proposed to function as a Rab5 effector to mediate early endosome fusion probably in specific endosome subpopulations. Required for fusion of endosomes and autophagosomes with lysosomes. Involved in cargo transport from early to late endosomes and required for the transition from early to late endosomes. Involved in the retrograde Shiga toxin transport.
Synonyms: hVPS11; RNF108; PEP5; DYT32; END1; HLD12; HLD12; DYT32
Gene: Protein-coding gene on chromosome 11 (119,067,789 to 119,082,753, forward strand). Ensembl gene ENSG00000160695.
Subcellular location: Endosome; Late endosome membrane; Lysosome membrane; Early endosome; Cytoplasmic vesicle; Cytoplasmic vesicle, autophagosome; Cytoplasmic vesicle, clathrin-coated vesicle
Subcellular location (Human Protein Atlas): Cytosol
Pathways (Reactome):
Disease: SARS-CoV-2 modulates autophagy
Genetic constraint (gnomAD): Loss-of-function variants: 51 observed, 107.94 expected, observed/expected ratio (o/e) 0.47, 90% interval 0.38 to 0.6. The upper end of that interval is the gene's LOEUF score, 0.6, which puts it in group 2 of 6, group 1 being the genes least tolerant of losing a copy. Missense variants: 936 observed, 1,225.8 expected, observed/expected ratio (o/e) 0.76, 90% interval 0.72 to 0.81. Synonymous variants: 447 observed, 476.38 expected, observed/expected ratio (o/e) 0.94, 90% interval 0.87 to 1.01.
Gene-disease validity (ClinGen):
ClinGen rates the evidence that VPS11 causes each of these diseases.
VPS11-related neurological disorder (autosomal recessive): Definitive. Any neurological disorder in which the cause of the disease is a mutation in the VPS11 gene.
Homologues: Orthologues: macaque VPS11 (99% identical), dog VPS11 (98% identical), pig VPS11 (98% identical), rabbit VPS11 (98% identical), mouse Vps11 (98% identical), rat Vps11 (98% identical), guinea pig VPS11 (97% identical), chimpanzee VPS11 (94% identical), tropical clawed frog vps11 (78% identical), zebrafish vps11 (74% identical), Caenorhabditis elegans vps-11 (28% identical), Drosophila melanogaster Vps11 (18% identical). Paralogues in human: VPS18 (14% identical).
Diseases named in the same sentence as VPS11 in open-access papers:
VPS11 is named in the same sentence as 59 diseases in open-access papers, as found by Europe PMC text mining. Sharing a sentence is not in itself a finding about the gene and the disease. The quoted sentences say what the papers report.
Dystonia (6 papers, 2018 to 2026). An abnormally increased muscular tone that causes fixed abnormal postures. "Given the consistency of clinical, molecular and histological data between these independent cases, it appears henceforth acceptable to consider that VPS11-associated clinical spectrum encompasses both, a white-matter pathology and dystonia." (PMID 41551069, 2026). "While acknowledged as a cause of hypomyelinated leukodystrophy, VPS11-associated dystonia was described in a single patient." (PMID 41551069, 2026). "We report here a case of VPS11-associated dystonia concerning a female patient born at term from a consanguineous union without family history of neurological disorders." (PMID 41551069, 2026). "VPS11 mutations are associated with broader neurodegenerative phenotypes, including dystonia and myoclonus in some cases, but usually accompanied by spasticity, cerebral atrophy, or peripheral neuropathy." (PMID 40584247, 2025). "Variants in the genes encoding for the HOPS complex have been associated with the etiopathogenesis of inherited dystonia (i.e., VPS16, VPS41, and VPS11)." (PMID 40655316, 2025). "Mutations in core proteins (VPS11, VPS16, VPS18, and VPS33) have been linked with multiple neurological disorders, including mucopolysaccharidosis (MPS), genetic leukoencephalopathy (gLE), and dystonia." (PMID 39000367, 2024). "Recent discoveries have expanded the genetic landscape of dystonia, identifying novel contributors such as AOPEP, VPS11, VPS16, and EIF2AK2." (PMID 40584247, 2025).
Leukoencephalopathy (4 papers, 2016 to 2024). This term describes abnormality of the white matter of the cerebrum resulting from damage to the myelin sheaths of nerve cells. "Our study establishes that defects in VPS11 are a novel cause of leukoencephalopathy, and identifies the C846G as an AJ founder mutation, thus providing valuable knowledge for genetic counseling in the affected families and in predicting disease risk." (PMID 27120463, 2016). "In summary, our study identifies a homozygous mutation in VPS11 as causative in a novel leukoencephalopathy disorder associated with dysfunctional autophagy-lysosome trafficking pathway, and implicates VPS11 as a potential therapeutic drug target for this devastating infantile disease." (PMID 27120463, 2016). "Furthermore, zebrafish harboring a vps11 mutation with abolished RING-H2 domain exhibits reduced myelination and significant neuronal death, confirming an essential role for VPS11 in CNS development and substantiates the causality of the C846G mutation in leukoencephalopathy." (PMID 27120463, 2016). "Major leukoencephalopathy manifestations in five individuals from three AJ families with homozygous VPS11: c.2536T>G (p.C846G)." (PMID 27120463, 2016). "In addition, progressive hypomyelination was also reported in vps11 mutant zebrafish, which was suggested as a model to study the human hypomyelinating disease genetic leukoencephalopathy." (PMID 39000367, 2024).
developmental delay (3 papers, 2016 to 2022). "A founder mutation in the human endolysosomal trafficking protein VPS11 has been identified in Ashkenazi Jewish patients manifesting classic gLE symptoms of hypomyelination, developmental delay, motor and systemic deficits." (PMID 35241734, 2022).
melanoma (3 papers, 2013 to 2025). A malignant, usually aggressive tumor composed of atypical, neoplastic melanocytes. "Since our data suggests inactivating mutations in vps11 lead to activation of autophagy, it is plausible that melanocytes containing these mutations are more susceptible to development of melanoma." (PMID 23724125, 2013). "Further examination of melanoma models in vps11 loss of function backgrounds may shed light on mechanisms for activating autophagy during melanoma progression." (PMID 23724125, 2013).
Cerebral atrophy (2 papers, 2023 to 2025). Atrophy (wasting, decrease in size of cells or tissue) affecting the cerebrum. "Variants in multiple genes regulating endosomal trafficking and/or fusion of secretory vesicles [such as SMPD4, WDFY3, TRAPPC4, RAB18, VPS13B, EXOC7, EXOC8, VPS11], have been associated with the occurrence of microcephaly, cerebral atrophy, and neurodevelopmental delay." (PMID 36538041, 2023).
hypomyelinating leukodystrophy (2 papers, 2022 to 2026). "•VPS11 is associated with hypomyelinated leukodystrophy affecting children." (PMID 41551069, 2026).
breast carcinoma (1 paper, 2019). "For ERα, these results were confirmed by assessing the effects of Vps11/18 levels on a few representative endogenous ERα target genes in ERα-positive breast cancer cells." (PMID 31015428, 2019). "Considering the fact that Vps11/18 are regulators of ERα, they could be prognostic markers for ERα-positive breast cancer patients." (PMID 31015428, 2019). "Similarly to what we had seen with exogenous ERα in HEK293T cells, the knock-down and overexpression of Vps11/18 in MDA-MB-134 breast cancer cells increased and decreased expression of endogenous ERα target genes, respectively." (PMID 31015428, 2019). "Note that repression of endogenous ERα target genes by Vps11/18 could be demonstrated with MCF-7 breast cancer cells as well, indicating that the phenomenon is independent of a specific cell line." (PMID 31015428, 2019). "Indeed, we found that breast cancer patients with high expression levels of Vps11/18 have a higher probability of relapse-free survival, For gastric cancer, which is ERα-independent, the clinical value of high expression of Vps11/18 is exactly opposite." (PMID 31015428, 2019).
malaria (1 paper, 2025). Malaria is a serious and sometimes fatal disease caused by a parasite that commonly infects a certain type of mosquito which feeds on humans. "Our data suggest that a CORVET-like or HOPS-like complex may play a role in endosomal trafficking in malaria parasites, but the specific subunits, besides the core VPS11 and VPS18, and the interaction with the corresponding Rab proteins, remains to be elucidated." (PMID 40198740, 2025). "In the case of the malaria parasite, the DV could be considered to be a lysosome-like organelle and our results suggest that VPS11 and 18 play a role in the fusion of HCC containing vesicles with the DV membrane rather than in the initial steps of cytostome formation and HCC uptake and transport." (PMID 40198740, 2025). "To test whether the core malaria parasite HOPS/CORVET complex might function in early endosomes, we co-localized VPS11 with Rbns5 and Rab5b, proteins known to be critical for the delivery of endocytosed hemoglobin via early endosomes to the DV." (PMID 40198740, 2025).
parasitemia (1 paper, 2025). "To analyse the importance of the VPS11, VPS16 and VPS18 HOPS/CORVET core subunits for blood stage development, we monitored the parasitemia of synchronised cultures grown without (control) or in presence of rapalog over two replication cycles (4 days) using flow cytometry." (PMID 40198740, 2025).
retinal degeneration (1 paper, 2022). Degeneration of the retina. "Future work on Vps11 mutant mice, which develop slower than zebrafish during early development, may give some insight into any underlining contribution of retinal degeneration to Vps11-dependent vision loss." (PMID 35241734, 2022). "The early retinal degeneration phenotype in the vps11(plt) mutants may result from the constraints of the rapid embryonic development of zebrafish, driving an accelerated and/or exacerbated neuronal degeneration pathology." (PMID 35241734, 2022). "A previous report showed a retinal degeneration phenotype in vps11(plt) mutants at 5dpf10, which could account for the OKR defect we observed in vps11(plt) and vps11(−/−) mutants." (PMID 35241734, 2022).
tumor (5 papers, 2016 to 2025). "Here, we further demonstrated that FOXM1D, acting as an adhesive protein, continues to interact with multiple proteins such as PKM2, the NF‐κB subunits of p65 and p50, importin 4, and VPS11, and thus promotes tumor glycolysis and angiogenesis." (PMID 33314660, 2021). "The increased VEGFA is secreted extracellularly via exosomes, an event potentiated by the interaction of FOXM1 with VPS11, eventually promoting tumor angiogenesis." (PMID 33314660, 2021).
infection (4 papers, 2011 to 2023). The state of being infected such as from the introduction of a foreign agent such as serum, vaccine, antigenic substance or organism. "Null mutants lacking the genes RIM101, CZF1,ALS3, HGC1, TUP1,TEC1, TPK1, TPK2,RAS1, or VPS11 showed significantdifferences at all analyzed stages of infection (adhesion, invasion, damage)." (PMID 21407800, 2011). "As found previously, infection with wild type S protein carrying MHV was reduced after gene silencing of RAB5, RAB7, VPS11, and VPS41 (red bars)." (PMID 25375324, 2014). "Silencing of NSF, required for transport from early to late endosomes, or of the HOPS subunits VPS11 and VPS41, which are involved in late endosome to lysosome maturation, all resulted in severely reduced MHV infection (turquoise and light green, respectively)." (PMID 25375324, 2014). "On the other hand, infection with MHV-S2′FCS was significantly diminished by downregulation of the early endosomal proteins RAB5B and RAB5C, but not of the late endosomal proteins RAB7A and RAB7B or the HOPS complex components VPS11 and VPS41 (blue bars)." (PMID 25375324, 2014).
cancer (1 paper, 2019). A tumor composed of atypical neoplastic, often pleomorphic cells that invade other tissues. "The involvement of Vps11/18 in cancer initiation and progression may be cancer type-specific and linked to their specific effects on the underlying signaling pathways." (PMID 31015428, 2019).
VPS11 also shares sentences with these, for which no sentence is quoted: cervical cancer (4 papers); cortical blindness (3); Ataxia (2); Intellectual disability (2); neurological disorders (2); Obesity (2); optic atrophy (2); atherosclerosis (1); autoimmune disease (1); bacterial infections (1); Bardet-Biedl syndrome (1); Chagas disease (1); Cognitive impairment (1); colon cancer (1); colorectal cancer (1); diabetes (1); endometrioid endometrial carcinomas (1); endometriosis (1); endothelial dysfunction (1); gastric cancer (1); Hypertension (1); hypomyelinating leukodystrophy 11 (1); Infantile onset (1); ischemia (1); Joubert syndrome (1); Kohlschutter’s syndrome (1); leprosy (1); lysosomal storage disease (1); microcephaly (1); movement disorder (1).
A further 16 diseases each share a sentence with VPS11 in 1 paper.